ENSG00000267110 (novel transcript)
Gene: Protein-coding gene on chromosome 19 (55,154,757 to 55,160,671, reverse strand). Ensembl gene ENSG00000267110.
Genetic constraint (gnomAD): Missense variants: 207 observed, 213.57 expected, observed/expected ratio (o/e) 0.97, 90% interval 0.87 to 1.09. Synonymous variants: 71 observed, 89.3 expected, observed/expected ratio (o/e) 0.8, 90% interval 0.66 to 0.97.